TWF1 (twinfilin actin binding protein 1)
Description:
Actin-binding protein involved in motile and morphological processes. Inhibits actin polymerization, likely by sequestering G-actin. By capping the barbed ends of filaments, it also regulates motility. Seems to play an important role in clathrin-mediated endocytosis and distribution of endocytic organelles (By similarity).
Synonyms: PTK9; A6
Tractability: Small molecule: a structure with a bound ligand is known. PROTAC: ubiquitination databases record sites on it; its protein half-life has been measured.
Gene: Protein-coding gene on chromosome 12 (43,793,460 to 43,806,328, reverse strand). Ensembl gene ENSG00000151239.
Subcellular location: Cytoplasm; Cytoplasm, cytoskeleton
Subcellular location (Human Protein Atlas): Cytosol
Pathways (Reactome):
Sensory Perception: Sensory processing of sound by inner hair cells of the cochlea; Sensory processing of sound by outer hair cells of the cochlea
Signal Transduction: RHOBTB2 GTPase cycle
Gene Ontology:
Molecular function: actin binding; ATP binding; cadherin binding; protein binding; protein tyrosine kinase activity; actin filament binding; actin monomer binding; phosphatidylinositol-4,5-bisphosphate binding; protein-containing complex binding
Biological process: actin filament depolymerization; barbed-end actin filament capping; negative regulation of actin filament polymerization; positive regulation of neuron projection development; regulation of lamellipodium assembly; positive regulation of cardiac muscle hypertrophy
Cellular component: cytosol; focal adhesion; actin cytoskeleton; actin filament; cell-cell junction; cytoplasm; filopodium; myofibril; perinuclear region of cytoplasm; ruffle membrane; cytoskeleton
Genetic constraint (gnomAD): Loss-of-function variants: 6 observed, 19.66 expected, observed/expected ratio (o/e) 0.31, 90% interval 0.17 to 0.6. The synonymous counts are far from expectation, so gnomAD's model fits this gene poorly and the ratio says little. Missense variants: 189 observed, 260 expected, observed/expected ratio (o/e) 0.73, 90% interval 0.64 to 0.82. Synonymous variants: 63 observed, 87.01 expected, observed/expected ratio (o/e) 0.72, 90% interval 0.59 to 0.89.
Homologues: Orthologues: macaque TWF1 (99% identical), dog TWF1 (98% identical), chimpanzee TWF1 (97% identical), rabbit TWF1 (95% identical), mouse Twf1 (95% identical), rat Twf1 (95% identical), guinea pig TWF1 (92% identical), pig TWF1 (92% identical), tropical clawed frog twf1 (80% identical), zebrafish twf1b (72% identical), zebrafish twf1a (57% identical), Drosophila melanogaster twf (48% identical), and 1 more. Paralogues in human: TWF2 (65% identical).
Diseases named in the same sentence as TWF1 in open-access papers:
TWF1 is named in the same sentence as 52 diseases in open-access papers, as found by Europe PMC text mining. Sharing a sentence is not in itself a finding about the gene and the disease. The quoted sentences say what the papers report.
breast cancer (12 papers, 2015 to 2025). A primary or metastatic malignant neoplasm involving the breast. "TWF1 has also been linked to breast cancer progression, while our study indicated that FANCA alterations negatively impacted TWF1 expression." (PMID 39844043, 2025). "In another finding, miRNA-30c regulates invasion of breast cancer by targeting the cytoskeleton network genes encoding Twinfilin 1 (TWF1) and Vimentin (VIM), both of which regulate EMT." (PMID 38540304, 2024). "Recent studies have reported that TWF1 has a close association with breast cancer, and miR-30c has been proposed to directly target TWF1, leading to inhibition of chemotherapy resistance and inhibit tumor invasion of human breast tumor." (PMID 34113576, 2021). "TWF1 is overexpressed in multiple cancers, including lung adenocarcinoma, breast cancer, and pancreatic cancer, and predicts poor outcomes." (PMID 40362400, 2025). "TWF1 was also identified as a predicted target of miR-674-3p, which was significantly upregulated in radiation-induced rat mammary cancer compared to normal mammary tissues." (PMID 36140805, 2022). "TWF1 depletion in breast cancer cell line MDA-MB-231 cells drastically reduced vinculin positive focal adhesions, suppressed organization of F-actin, and enhanced the EMT wherein cells acquire spherical morphology." (PMID 34113576, 2021). "We found that the phosphorylation level of S143 of TWF1 in primary tumor tissues of ovarian cancer and breast cancer is significantly reduced." (PMID 34113576, 2021). "miR-206 also suppresses stem-like and metastatic features of breast cancer by regulating the TWF1- MKL1-IL11 pathway." (PMID 34621748, 2021). "Lastly, miR-206/TWF1/MKL1-SRF/IL-11 signaling pathway inhibits breast cancer initiation and progression." (PMID 29162923, 2017). "And it was found that miR-30c significantly suppressed lung metastases of breast cancer cells by targeting TWF1 and regulating IL-11-pSTAT3 signaling pathway in vivo." (PMID 29100303, 2017). "Other miRNAs recently implicated in breast cancer include miR-100, shown to target SMARCA5, SMARCD1, and BMPR2 genes, which directly influence tumor cell proliferation, and miR-30c, known to target TWF1 and IL-11, both of which are expressed in the MaSC/basal lineage." (PMID 26080807, 2015). "Western blot data indicated that miR-1 overexpression significantly downregulated WASF2, TWF1, CNN3, TMSB4X and CORO1C, showing that miR-1 could inhibit breast cancer cell metastasis by targeting the WASF2, TWF1, CNN3, TMSB4X and CORO1C genes." (PMID 28159933, 2017). "Recent studies have proposed Twinfilin Actin Binding Protein 1 (TWF1) as a putative driver gene in lung cancer, pancreatic cancer and breast cancer, however a systematic pan-cancer analysis has not been carried out." (PMID 34113576, 2021).
pancreatic cancer (8 papers, 2019 to 2025). "In pancreatic cancer, TWF1 downregulation by miR-142-3p reduces cell proliferation and EMT, while enhancing apoptosis in gemcitabine-resistant pancreatic cancer cells." (PMID 40362400, 2025). "TWF1 has been identified as an important gene in lung, breast, and pancreatic cancer in recent investigations." (PMID 36128444, 2022). "TWF1 gene encodes Twinfilin, an actin monomer-binding protein that promotes EMT in pancreatic cancer tissues." (PMID 34249670, 2021). "In the development and progression of pancreatic cancer, miR-30 c had vital functions by targeting twinfilin 1 (TWF1) or DNA topoisomerase II alpha gene (TOP2A)." (PMID 34503377, 2021). "Moreover, lncRNA SBF2-AS1 acts as a ceRNA sponging miRNA-142-3p to participate in gemcitabine resistance in human pancreatic cancer via upregulating Twinfilin Actin Binding Protein 1 (TWF1)." (PMID 32976115, 2020).
cardiac hypertrophy (5 papers, 2011 to 2024). "IGF/IGF‐1 and twinfilin actin‐binding protein 1 (TWF1) are inhibited by miR‐1, which reduces cardiac hypertrophy and cardiac fibrosis." (PMID 39502130, 2024). "Further studies demonstrate that miR-1 prevents cardiac hypertrophy by suppressing heart and neural crest derivatives expressed 2 (Hand2), and by inhibiting the activity of insulin-like growth factor (Igf1) and extracellular matrix remodeling factor, twinfilin 1 (Twf1)." (PMID 27213331, 2016).
breast tumor (4 papers, 2017 to 2025). "The human breast tumor biomarker miR-30c can inhibit tumor invasion by targeting the cytoskeletal network genes encoding TWF1 and vimentin." (PMID 28159933, 2017).
lung carcinoma (4 papers, 2013 to 2022). "Concerning miR-486-5p, it was also recently demonstrated that the suppression of the twinfilin actin-binding protein 1 (TWF1) induced by this miRNA improved the susceptibility to Cisplatin of lung cancer cell lines both in vitro and in vivo." (PMID 35337095, 2022). "Research related to ABPs and lung cancer has mainly focused on twinfilin-1 (TWF1) and fascin-1 and on the relationships between VASP, profilin-1, and cofilin-1." (PMID 34194957, 2021). "Regarding lung cancer, we explored the datasets of the TCGA-LUSC (n=501) and TCGA-LUAD (n=515) and found a correlation between the high expression of TWF1 and late clinical staging (P<0.01) poor OS prognosis (P<0.001), poor DFS (P<0.01) specific for LUAD but not for LUSC." (PMID 34113576, 2021).
gastric cancer (2 papers, 2017 to 2021). A primary or metastatic malignant neoplasm involving the stomach. "In the present investigation, miR-1 was shown to simultaneously inhibit tumor growth and metastasis of breast and gastric cancers by synchronously targeting CDK4 and TMSB4X, CNN3, TWF1, CORO1C and WASF2 genes." (PMID 28159933, 2017). "In this context, the miR-1-mediated downregulation of the TMSB4X, CNN3, TWF1, CORO1C and WASF2 genes led to the inhibition of tumor cell metastasis of breast and gastric cancers." (PMID 28159933, 2017).
liver cancer (2 papers, 2021 to 2025). An epithelial or non-epithelial malignant neoplasm that arises from the liver. "Using the Human Protein Atlas (HPA) algorithm, we analyzed mRNA expression data of 362 liver cancer patients from the TCGA HCC cohort, and demonstrated that high TWF1 expression is associated with lower survival rates and a poor prognosis." (PMID 40362400, 2025).
lung adenocarcinoma (2 papers, 2021 to 2025). A carcinoma that arises from the lung and is characterized by the presence of malignant glandular epithelial cells. "We found that over-expression of TWF1 generally predicted poor OS for patients with tumors with high TWF1 expression, such as mesothelioma, lung adenocarcinoma, cervical cancer and pancreatic adenocarcinoma." (PMID 34113576, 2021). "In lung adenocarcinoma, downregulation of TWF1 suppresses invasion, migration, and autophagy." (PMID 40362400, 2025).
melanoma (2 papers, 2021 to 2024). A malignant, usually aggressive tumor composed of atypical, neoplastic melanocytes. "The transfection efficiency of SK-MEL-2 melanoma cells with miR-204-5p mimics was also indirectly verified via detecting the mRNA expression levels of TWF1 gene." (PMID 37304648, 2021). "Herein, the expression levels of TWF1 were significantly reduced by 1.94 times in SK-MEL-2 melanoma cells transfected with positive control miRNAs compared with those transfected with NC ones." (PMID 37304648, 2021). "The successful transfection of SK-MEL-2 melanoma cells with miR-204-5p mimics was confirmed directly and indirectly via detecting the mRNA expression levels of TWF1." (PMID 37304648, 2021). "In 2017, Patel used the CRISPR system, together with a machine-learning computational model, to identify genes essential for tumor progression in melanoma cell lines, such as collagen type XVII alpha 1 (COL17A1), twinfilin-1 (TWF1), microRNA 101-2 (Hsa-Mir-101-2) and ribosomal protein L23 (RPL23)." (PMID 39696697, 2024).
Obesity (2 papers, 2023). Accumulation of substantial excess body fat. "Our findings provide novel insights regarding the mechanism underlying TWF1 expression and myogenesis in the background of obesity." (PMID 37190023, 2023). "This study suggests that a reduction in TWF1 expression underlies myogenic differentiation impairment by SFA, and this may be an etiology of muscle wasting in obesity." (PMID 37047312, 2023). "Despite this, the epigenetic regulation and role of TWF1 in myogenesis remain unknown under conditions related to muscle wasting, such as obesity, oxidative stress, and inflammation." (PMID 37190023, 2023). "Since TWF1 is required for myogenic differentiation and miR-665-3p levels are increased in obesity, we next investigated whether TWF1 and miR-665-3p expressions are affected by PA treatment in C2C12 cells." (PMID 37190023, 2023). "Thus, this study elucidated the role of miR-302a in the regulation of TWF1 and myogenesis and suggested a possible mechanism for miRNA-mediated muscle wasting in obesity." (PMID 37047312, 2023). "A reduction in TWF1 expression by PA has been first demonstrated in this study, which suggests that this could contribute to the pathogenesis of sarcopenia in obesity by connecting fat deposition to impaired myogenesis." (PMID 37047312, 2023). "In regards to the mechanism by which SFAs impair myogenic differentiation, the present study shows, for the first time, that PA suppresses TWF1 expression and suggests this suppression may be an etiology of muscle wasting in obesity." (PMID 37190023, 2023). "However, the role played by TWF1 in the pathogenesis of muscle wasting, particularly in obesity, is largely unknown." (PMID 37047312, 2023). "The results revealed that the HFD-induced obese mice had decreased TWF1 expression and increased miR-665-3p expression in the gastrocnemius muscle, indicating that obesity may negatively affect the expression of TWF1 in skeletal muscle while increasing miR-665-3p levels." (PMID 37190023, 2023). "Nevertheless, the molecular mechanisms underlying the epigenetic regulation and biological significance of TWF1 in obesity and muscle wasting have not been explored." (PMID 37047312, 2023).
uterine tumors (2 papers, 2021 to 2022). "The frequency of TWF1 alteration (>5%) is the highest in uterine tumors with “mutation” as the primary type." (PMID 36128444, 2022). "According to our analysis, the frequency of TWF1 alteration (>5%) is the highest in uterine tumors with “mutation” as the primary type." (PMID 34113576, 2021).
cholestasis (1 paper, 2021). Impairment of the bile flow caused by obstruction within the liver, or outside the liver in the bile duct system. "Interestingly, twf-1 expression increased in the DDC feeding model of cholestasis and in human PSC samples, and Twf-1−/− mice subjected to DDC had reduced biliary senescence and SASP." (PMID 34993234, 2021).
colon cancer (1 paper, 2018). "Six genes (aldehyde dehydrogenase 2, neural precursor cell expressed, developmentally down-regulated 9, filamin A, lamin B receptor, twinfilin actin binding protein 1, serine and arginine rich splicing factor 1) were closely related to the OS of colon cancer patients." (PMID 30155352, 2018). "However, no study has yet reported the role of LBR and TWF1 in CRC and therefore their role needs be investigated further in colon cancers." (PMID 30155352, 2018).
deafness (1 paper, 2024). An inherited or acquired condition characterized by the complete loss of the ability to hear from one or both ears. "An association study in dogs identified TWF1 as a candidate gene for deafness, and this gene has potential roles in hair-bundle development and melanocyte dendricity." (PMID 39080565, 2024).
developmental delay (1 paper, 2018). "So far no paper published has reported that TWF1 or TMEM117 is connected with developmental delay." (PMID 30155906, 2018).
Intellectual disability (1 paper, 2020). "We propose PUS7L and TWF1 as likely candidate genes on the telomeric region of 12q12 for the intellectual disability and craniofacial anomalies seen in DCP250361." (PMID 31963867, 2020). "Additionally, we suggest PUS7L and TWF1 as candidate genes for intellectual disability and craniofacial anomalies on the telomeric region of 12q12." (PMID 31963867, 2020).
mesothelioma (1 paper, 2021). A usually malignant and aggressive neoplasm of the mesothelium which is often associated with exposure to asbestos. "High expression of TWF1 was associated with poor prognosis of OS (Overall survival) for cancers including CESC (P=0.045), LUAD (P=0.00014), MESO (Mesothelioma) (P=0.0016) and PAAD (Pancreatic adenocarcinoma) (P=0.031)." (PMID 34113576, 2021).
prostate adenocarcinoma (1 paper, 2021). "In contrast, TWF1 showed lower expression in KIRC (Kidney Renal Clear Cell carcinoma), PRAD (Prostate Adenocarcinoma) (P<0.001), and READ (Rectum adenocarcinoma) (P<0.05) relative to the corresponding control tissues." (PMID 34113576, 2021).
tumor (21 papers, 2008 to 2025). "We also assessed the mutation burden of TWF1 in cancer and the TWF1-associated survival of cancer patients, compared the phosphorylation of TWF1 between normal and primary tumor tissues and explored putative functional mechanisms in TWF1-mediated oncogenesis." (PMID 34113576, 2021). "TWF1 is differentially associated with the prognosis of different tumor cases." (PMID 34113576, 2021). "The difference in TWF1 expression levels in different tumor types may reflect distinct underlying functions and mechanisms." (PMID 34113576, 2021). "To explore expression profile of TWF1 across various tumor types in a pan-cancer analysis, we used dataset available via TCGA Project and GEO databases." (PMID 34113576, 2021). "We divided cancer cases into high expression group and low expression group according to the expression level of TWF1, and then TCGA and GEO datasets were used to study the correlation between TWF1 expression and prognosis of different tumor patients." (PMID 34113576, 2021). "Based on our analysis, the expression level of TWF1 and total protein of TWF1 in the tumor tissues of BRCA is higher than the corresponding control tissues." (PMID 34113576, 2021). "In case of tumors, where normal tissue data was not available in TCGA, we further assessed the expression differences of TWF1 between the tumor and normal tissues using the GTEx dataset." (PMID 34113576, 2021). "Here, we set out to explore the role of TWF1 in 33 tumor types using TCGA (The Cancer Genome Atlas), GEO (Gene Expression Omnibus) dataset, Human Protein Atlas (HPA), and several bioinformatic tools." (PMID 34113576, 2021). "The GO|KEGG pathway analysis revealed “focal adhesion” and “vesicle transportation” among the top hits, suggesting these pathways in the effect of TWF1 on tumor pathogenesis." (PMID 34113576, 2021). "We further explored the relationship between TWF1 expression and TMB (Tumor mutational burden) and MSI (Microsatellite instability) across all tumors represented in TCGA." (PMID 34113576, 2021). "Next, we used the TIMER2 to study the differential expression of TWF1 between tumor and adjacent normal tissues for tumors represented in the TCGA repository." (PMID 34113576, 2021). "Recent studies demonstrate that miR-30c, one of the well-known tumor suppressor miRNAs that promote cell death and inhibit tumor invasion, plays an important role in reversing chemotherapy resistance by regulating TWF1 and interleukin-11." (PMID 26526790, 2015). "Linear dodecapeptide peptide (BRBP1)-functionalized cholesterol- and distearoylphosphatidylcholine (DSPC)-based liposomes were developed to deliver paclitaxel and siRNA specific to the drug-resistant gene twinfilin-1 (TWF1) in TNBC tumor xenografts and in a brain metastatic mouse model (231-BR)." (PMID 37296869, 2023). "Mechanistically, it has been proposed that this link would be due, at least partially, to the decrease of the tumor suppressor microRNA-30c (miR-30c), which prevents tumor chemotherapy resistance by directly reducing twinfilin 1 (TWF1) levels and its secondary target, secreted IL-11." (PMID 35163731, 2022). "Nevertheless, it remains poorly understood whether TWF1 is involved in the oncogenesis of certain tumor types, or rather play a role in more common pathways driving tumor pathogenesis." (PMID 34113576, 2021). "In addition to expression profile comparison of TWF1 across tumor types, we also considered survival status, genetic alteration, protein phosphorylation and relevant cellular pathways." (PMID 34113576, 2021). "Next, we analyzed the expression pattern of TWF1 in different cell lines and non- tumor tissues." (PMID 34113576, 2021). "However, previous studies limited the evaluation of TWF1 to a few cancer types, and its role remain elusive in other tumor types." (PMID 34113576, 2021).